IL6 (interleukin 6)
Diseases named in the same sentence as IL6 in open-access papers (continued):
Sharing a sentence is not in itself a finding about the gene and the disease.
diabetic nephropathy (154 papers, 2009 to 2025). "Diabetic Nephropathy is associated with the deregulation of adipokines, hepatokines, and myokines such as resistin, adiponectin, leptin, interleukin-6 (IL-6), and other inflammatory markers." (PMID 37312105, 2023). "IL-9 was also strongly correlated with VEGF, TNFα and IL-6 all of which have all been previously implicated in diabetic nephropathy." (PMID 35445345, 2022). "Association of T2D with C1q SNP rs2920001 and diabetic nephropathy with IL-6 SNP rs1800795 were identified in the Greek population." (PMID 28067832, 2017). "The cytokine interleukin 6 (IL-6) is an essential regulator of the acute phase response associated with T2D and diabetic nephropathy." (PMID 20144192, 2010). "Patients with diabetic nephropathy and proteinuria had a positive association between the degree of proteinuria and inflammation, although restricted to IL-6 (r = 0.39, P < 0.05)." (PMID 19232095, 2009). "The nephropathy was successfully treated with tocilizumab, suggesting that IL-6 may cause diabetic nephropathy-like and/or arteriosclerotic-like nephropathy in patients with hypolipidemia, normal-range blood pressure, and normal glycemia." (PMID 39776937, 2024). "The risk estimates of the IL-6: omentin-1 ratio in the development of diabetic nephropathy." (PMID 39131026, 2024). "This study demonstrated that dietary intervention of very low carbohydrate diet in patients with underlying diabetic kidney disease was safe and associated with significant improvements in glycemic control, anthropometric measurements including weight, abdominal adiposity and IL-6." (PMID 34644368, 2021). "Nevertheless, both MMP-9 and IL-6 have been associated with pathogenesis of diabetic nephropathy." (PMID 27101382, 2016). "Altered expressions of (miR-122-5p, miR-486-5p, and miR-21-5p) in diabetic nephropathy suggest their involvement in these processes, while the selected inflammatory markers (IL-6, TNF-α, CRP) mediate DKD-related inflammation." (PMID 41318413, 2025). "In plasma we observed a non-significant 1.44-fold increase in IL-6 at post-treatment compared to baseline, whereas D ​+ ​Q reduced levels of plasma IL-6 in a population with diabetic kidney disease." (PMID 40274471, 2025). "Both IL-1b and IL-6 are elevated in several forms of inflammatory chronic kidney diseases, including diabetic kidney disease." (PMID 39334814, 2024). "A previous trial which utilized D+Q in a population with diabetic kidney disease reported reduced levels of plasma IL-6 after only 3 days of senolytic treatment." (PMID 38496619, 2024). "In our pursuit of identifying innovative biomarkers for the early detection of diabetic nephropathy, this study was crafted to explore the relationship between chemokines, omentin-1, interleukin-6, and microalbuminuria." (PMID 39131026, 2024). "As per the clinical data, the levels of IL-6 and IL-1β were increased in patients with diabetic nephropathy." (PMID 38202711, 2023). "It was reported in the literature that the increase in IL-18 levels was parallel with the increase in IL-6 levels, in diabetic nephropathy." (PMID 37736511, 2023). "Patients with diabetic nephropathy have elevated IL-6, and patients with dominant proteinuria have higher serum albumin levels than patients with microalbuminuria or normal albuminuria." (PMID 35299891, 2022). "IL-6 expression is increased in diabetic nephropathy, and levels correlate with glomerular basement membrane thickening." (PMID 35445345, 2022). "Shikano suggested that IL-6 promotes the growth of mesangial renal cells and seem to be a good indicator of diabetic nephropathy, especially the urinary levels." (PMID 35295847, 2022). "Various inflammatory stimuli, such as TNF-α, CCL-2, IL-1β, and IL-6, which drive chronic renal inflammation in diabetic kidney disease, have been shown to stimulate Saa3 production in mice." (PMID 35055081, 2022).
diabetic nephropathy (continued). "Previous studies have also shown that administration of exogenous antioxidants can inhibit diabetic nephropathy due to inhibition of oxidative stress, resulting in a decrease in the production of inflammatory cytokines such as IL-6 and TNF-α." (PMID 35685736, 2022). "In addtion, IHC staining also revealed that TNF-α, IL-1β and IL-6 signifificantly increased in diabetic nephropathy kidney, its secretion can be suppressed by treatment of A&P." (PMID 35057768, 2022). "According to clinical data, the concentration of IL-1β and IL-6 was increased in patients with diabetic nephropathy." (PMID 35956936, 2022). "Caffeic acid also had anti-inflammatory effects in the model of diabetic nephropathy (DN) mice by reducing renal IL-6, IL-1β, TNF-α, and MCP-1 levels." (PMID 35052518, 2021). "JAK2 and STAT3, playing key roles in the control of cell proliferation and inflammation, are the most important signal cascades involved in IL-6 transduction in the glomeruli and tubules of diabetic nephropathy." (PMID 34054555, 2021). "IL-6 is considered as a prototypical proinflammatory cytokine playing an important role in diabetic nephropathy." (PMID 32961903, 2020). "Blocking IL-6/STAT3 signaling defers inflammation responses central to the progression of diabetic nephropathy and atherogenic responses." (PMID 32802115, 2020). "Effector molecules of the innate immune system including C-reactive protein, interleukin-6, and tumor necrosis factor-α are increased in patients with diabetic kidney disease." (PMID 29910771, 2018). "It is known that among inflammatory cytokines, such as TNF-α and IL-6 are relevant to the development of diabetic nephropathy, with diverse actions potentially involved in the development of complications." (PMID 24886259, 2014). "In patients with diabetic nephropathy and proteinuria, IL-6, TNF-α and MRP8/14 were significantly and independently associated with CRAE after adjustment for age, gender, BMI, glucose, 24 h SBP, and eGFR." (PMID 19232095, 2009). "In this context, MRP8/14 was in our study positively associated with Interleukin-6 as marker for systemic inflammation and TNF-α as marker for metabolic driven inflammation in patients with diabetic nephropathy." (PMID 19232095, 2009). "The ethanol extract of LB can inhibit the activation of NF‐κB in the renal tissue of diabetic nephropathy rats and reduce the levels of serum TNF‐α and IL‐6, thereby reducing the renal pathological damage caused by inflammatory reactions and improving renal function." (PMID 41036511, 2025). "Podocyte hypertrophy observed in diabetic nephropathy (DN) may be related to IL-6 signaling through the activation of Janus kinase 2/signal transducer and activator of transcription 3 signaling pathway (JAK2/STAT3)." (PMID 41150807, 2025). "Inflammatory cytokines, such as interleukin (IL)-6, IL-8, IL-10, and IL-18, have also been reported in this context; for example, multiple studies have demonstrated that IL-6 signaling contributes to the progression of diabetic nephropathy." (PMID 40003909, 2025). "IL-6 promoted growth and proliferation of mesangial cells, glomerular basement membrane thickening, and glomerulosclerosis, all of which contribute to the development of diabetic kidney disease." (PMID 41009007, 2025). "Although several reports have examined serum BDNF in diabetes, few have systematically explored its relationships with vitamins D, B12, and folic acid, trace elements (zinc, calcium), and pro-inflammatory cytokines (IL-6, IL-12) in the context of diabetic nephropathy." (PMID 41142318, 2025). "As a result, there is a simultaneous increase in neutrophil count, accompanied by a decrease in tumor necrosis factor, KC, interleukin 6, and interleukin 1β,42–44 these factors exhibit a strong correlation with the onset and progression of diabetic nephropathy." (PMID 38095344, 2024). "The proportion of diabetic nephropathy subjects using the IL-6: omentin-1 ratio cut-off." (PMID 39131026, 2024).
diabetic nephropathy (continued). "Clinical studies of IL-6 signaling antagonism in diabetic kidney disease." (PMID 39723211, 2024). "In situ expression of IL-6 in diabetic nephropathy was significantly increased compared to a control group; hence higher IL-6 production may be associated with kidney injury in T2DM." (PMID 37996879, 2023). "Mesangial cell proliferation is the underlying pathophysiological feature of renal diseases such as IgA nephropathy, SLE and diabetic nephropathies, and markedly, the amount of urinary IL-6 correlated with the degree of cell proliferation, which stimulated the growth of rodent mesangial cells." (PMID 37189804, 2023). "Serum bilirubin levels are positively correlated with the levels of the antioxidative enzymes as superoxide dismutase, catalase, and glutathione peroxidase, while it is inversely correlated with C-reactive protein, TNF-α, interleukin (IL)-2, IL-6, and IL-10 release in diabetic kidney disease." (PMID 35327498, 2022). "However, serum IL-6 and TNFα have been reported to be used as predictors of kidney disease progression in diabetic nephropathy." (PMID 35350980, 2022). "Furthermore, the protective effect of kaempferol against streptozotocin-induced diabetic nephropathy has been proved to be associated with the downregulation of TNF-α and IL-6." (PMID 35837376, 2022). "In an exploratory analysis, we also studied interactions between IL-9, the albumin/creatinine ratio (ACR) and urinary cytokines linked to the progression of diabetic nephropathy: vascular endothelial growth factor (VEGF), interleukin-6 (IL-6) and tumor necrosis factor alpha (TNFα)." (PMID 35445345, 2022). "In addition, tetrandrine can reduce the levels of inflammatory factors TNF-α and IL-6 and elevate IL-10 level in rats with diabetic nephropathy (DN)." (PMID 35722158, 2022). "Additionally, crocin (20 mg/kg) mitigated TGF-β, NF-κB, and IL-6 expression levels following streptozocin-induced diabetic nephropathy in rats." (PMID 34956439, 2021). "Following its expression, IL-6 can function on various immune cells to trigger and/or increase inflammatory response, macrophage activation and fibrosis contributes to end organ damage such as diabetic nephropathy and neuropathy." (PMID 33858419, 2021). "As a cardinal event of diabetic kidney disease (DKD), whether the podocyte abnormalities are associated with IL‐6 signalling, especially classic or trans‐signalling respectively, remains unclear." (PMID 28881473, 2018). "The author suggested that blocking IL-6 and its downstream mediators such as IL-6R and gp130 may attenuate the progression of diabetic nephropathy (DN)." (PMID 28484449, 2017). "Interestingly, similar to IL-6, IL-18 has also been reported to be enhanced in serum and urine samples of patients with diabetic nephropathy compared to controlled subjects, and higher IL-18 levels in turn increase UAE as evidenced by many clinical studies." (PMID 28164134, 2017). "Trophic factors and cytokines, including vascular endothelial growth factor (VEGF), insulin growth factor (IGF), mitogenic cytokine, IL-8, IL-6, and TNF-α, have been implicated in the pathogenesis of diabetic retinopathy, diabetic nephropathy, and diabetic neuropathy." (PMID 26824041, 2016). "The drop in kidney levels of miR-451-5p and miR-16 could lead to unchecked increased expression of their target IL-6 and MMP-9 levels which are associated with the pathogenesis of diabetes nephropathy." (PMID 27101382, 2016). "Low levels of BDNF in patients with diabetic nephropathy may be related to several mechanisms, including inflammation and oxidative stress, because some interleukins inhibit the production of this protein (such as IL-6 and IL-12)." (PMID 41142318, 2025). "Besides, serum IL-6 levels are also elevated in diabetic nephropathy mice." (PMID 34790229, 2021).
diabetic nephropathy (continued). "Finally, besides the IL-6 rs1800795, other SNPs of IL-6 such as rs1800796, rs1800797, rs1524107, rs2069837, rs2069840, etc. might also play important roles in the development of diabetic nephropathy or T2DM." (PMID 33016995, 2020). "(TC-PLA NPs) exerted renal protective effects in STZ-induced diabetic nephropathy rats by reducing the expression of inflammatory factors (TNF-α, IL-6) and stabilizing renal function indicators (Scr, BUN)." (PMID 41373787, 2025). "In preclinical models, UA has been shown to lower inflammatory cytokines such as IL-6, TNF-α, and MCP-1 in diabetic kidney disease." (PMID 41374004, 2025). "A meta-analysis revealed that berberine significantly improved renal function indicators (such as BUN and SCR) and inflammatory factors (IL-6 and TNF-α) in animal models of diabetic nephropathy." (PMID 40661082, 2025). "The stimulation of IL6 and TNFα production elicited by FGF23 is abolished in diabetic nephropathy mouse models injected with the carboxy-tail peptide of FGF23, which prevents iFGF23 signaling." (PMID 38791495, 2024). "Many inflammatory cytokines, including interleukin-1 (IL-1), interleukin-8 (IL-8), interleukin-6 (IL-6), and tumor necrosis factor (TNF), play an important role in the development and progression of diabetic nephropathy." (PMID 37398707, 2023). "In STZ-induced diabetic nephropathy mice, APF also decreased the mRNA and protein expression of inflammatory factors such as TNF-α, IL-1-β, and IL-6, and also improved the damage of high glucose to renal mesangial cells by regulating autophagy." (PMID 37101717, 2023). "In humans, higher levels of MCP-1, IL-6, and TNF-α were found in biopsies of patients with diabetic nephropathy or morbid obesity." (PMID 37629165, 2023). "Serum IL-6, NF-κB, and MCP-1 levels are closely related to renal injury and poor prognosis in patients with diabetic nephropathy, and the combined assay is valuable for assessing patients' condition and prognosis." (PMID 35756496, 2022). "Current evidence supports the antioxidant and anti-inflammatory properties of resveratrol, but its relationship with the levels of some inflammatory cytokines such as IL-6 and TNF-α in animals with diabetic nephropathy needs further elucidation." (PMID 35355720, 2022). "This further confirmed a close correlation between serum IL-6, MCP-1, and NF-κB levels and the prognosis of patients with diabetic nephropathy, which is of clinical value for the prognostic assessment of the disease." (PMID 35756496, 2022). "Accordingly, the present study investigated the prognostic value of the combined assay of IL-6, NF-κB, and MCP-1 in diabetic nephropathy to provide a reference for future clinical practice." (PMID 35756496, 2022). "The purpose of the current study was to evaluate the role of oxidative markers AOPP, AGEs, MDA antioxidant GSH and inflammatory biomarkers IL-6, TNF-α, and MPO in diabetic nephropathy compared to controls and type 2 diabetics." (PMID 36363561, 2022). "Cytokines of inflammatory such as IL-6 and TNF-α play a pivotal role in kidney damage that can be used as indicators of diabetic nephropathy." (PMID 35685736, 2022). "It has been reported that SGLT2 inhibition attenuates inflammation, including levels of CRP, IL-6, and TNF-α, and the progression of diabetic nephropathy." (PMID 35676606, 2022). "Current evidence supports the antioxidant and anti-inflammatory properties of RSV, but its relationship with some inflammatory mediators such as IL-6 and TNF-α in animals with diabetic nephropathy needs further elucidation." (PMID 35355720, 2022). "Another clinical study in the same year suggested that after 11 days of DQ in patients with diabetic nephropathy, the expression of p16INK4A by senescent adipocytes was reduced and SASP levels (e.g., IL-6, IL-1α) were also decreased." (PMID 35897741, 2022).
diabetic nephropathy (continued). "The receiver operating characteristic (ROC) curve was drawn, and the area under the curve (AUC) was calculated to analyze the predictive value of combined detection of IL-6, MCP-1, and NF-κB in the prognosis of patients with diabetic nephropathy." (PMID 35756496, 2022). "Our research describes that inflammatory cytokines IL-6 and TNF-α levels in kidney tissue are significantly increased in streptozotocin-induced diabetic nephropathy rats, indicating that these rats have kidney damage." (PMID 35685736, 2022). "Interleukin 1 (IL-1), IL-6, IL-18, and tumor necrosis factor (TNF) are considered the crucial inflammatory cytokines in diabetic nephropathy." (PMID 35295847, 2022). "The expression of IL-6 and MCP-1 increased more significantly in patients with diabetic nephropathy with more severe urinary protein and overall disease exacerbation." (PMID 35756496, 2022). "The expression of miR-93-5p was shown to be decreased in diabetic nephropathy, again under the regulation of lncRNA, and its inhibition reduced fibrosis and inflammation with a reduction in TNF-α, IL-6, and IL-1β." (PMID 36499023, 2022). "In the glomerular sclerosis and matrix deposition of diabetic nephropathy, JAK2/STAT3 is the most important signal cascade involved in IL-6 transduction." (PMID 34054555, 2021). "For instance, inhibiting the levels of inflammatory cytokines including IL-6, IL-1b, and TNF-α in PRAT through upregulation of heme oxygenase system reduced renal inflammation and ameliorated diabetic nephropathy in rats." (PMID 34298949, 2021). "Conversely, PTX-3, IL-6, and hs-CRP levels were decreased after periodontal treatment only in PD patients with diabetic nephropathy." (PMID 31382656, 2019). "These include IL-1, IL-6, IL-18, and TNF-α which are mainly involved in the development and progression of diabetic nephropathy." (PMID 28164134, 2017). "In an in vivo study, Pal and colleagues demonstrated that mangiferin suppressed inflammatory lesion in diabetic nephropathy by reducing TNF-α and IL-6 levels along with reduced expression of IKK and subsequent inhibition of NF-κB pathway activation." (PMID 28181586, 2017). "The inhibitory effects on the levels of interleukin-2, interleukin-6, interleukin-10, and tumor necrosis factor-α in serum and kidney revealed the protection of PHC against diabetic nephropathy." (PMID 27034961, 2016). "A previous study also demonstrated that azelnidipine significantly decreased plasma levels of monocyte chemoattractant protein-1, IL-6, hsCRP, TNF-α, 8-epi-prostaglandin F2α, and 8-hydroxydeoxyguanosine in patients with diabetic nephropathy." (PMID 21906391, 2011). "Similarly, Aldahr and El-Kader conducted a study in Saudi Arabia, which found that aerobic exercise significantly improved kidney function, reduced oxidative stress, and lowered inflammatory markers such as IL-6 and TNF-α in patients with diabetic nephropathy." (PMID 39569233, 2024). "This may impede the loss of podocytes, which in turn improves glycolipid metabolism (AST, LDH), inflammation (IL-6) and oxidative stress (HO-1), as well as the fibrinogen system (tPA, PAI-1) that accompanies diabetic nephropathy." (PMID 39830349, 2024). "Moreover, SGLT2i have been shown to decrease the circulating levels of IL-6, tumor necrosis factor receptor-1 (TNF receptor-1), matrix metalloproteinase-7, and fibronectin-1, all acting on essential key points in diabetic kidney disease." (PMID 39000165, 2024). "Furthermore, investigatingtheir anti-diabetic nephropathy activity showed that ECS and BCS significantlyinhibited the production of interleukin-6 (IL-6) in mesenchymal cells stimulatedwith high glucose." (PMID 37579272, 2023). "In addition, IL-6, TNFα, and MPO levels were also increased in case of diabetes nephropathy compared to controls." (PMID 36363561, 2022).